NORAD (non-coding RNA activated by DNA damage)
Diseases named in the same sentence as NORAD in open-access papers (continued):
Sharing a sentence is not in itself a finding about the gene and the disease.
atherosclerosis (11 papers, 2020 to 2024). A disease characterized by the build-up of fatty material and calcium deposition in the arterial wall resulting in partial or complete occlusion of the arterial lumen. "Recently, NORAD was found to play a critical role in atherosclerosis progression by regulating endothelial cells." (PMID 37418054, 2024). "At the same time, the lncRNA NORAD knockdown alleviated vascular endothelial cell injury and atherosclerosis development in both models (in vitro and in vivo)." (PMID 35055117, 2022). "Regarding LINC00657 (NORAD), our results are in line with a study which found that LINC00657, which is expressed in vascular endothelial cells, induced angiogenesis during atherosclerosis through the upregulation of VEGF, MMP-2, and MMP-9." (PMID 35237654, 2021). "Ultrasound imaging, Oil Red O staining, and H&E staining were utilized to evaluate the effect of lncRNA NORAD knockdown on atherosclerosis." (PMID 34307380, 2021). "Second, knockdown of lncRNA NORAD aggravated ox-LDL-reduced or atherosclerosis-decreased VEGF expression in HUVECs and thoracic aorta of mice to ameliorate vascular endothelial cell injury and atherosclerosis development." (PMID 34307380, 2021). "This study demonstrated that lncRNA NORAD induced vascular endothelial cell injury and atherosclerosis through suppressing VEGF transcription by enhancing H3K9 deacetylation." (PMID 34307380, 2021). "This study indicated the effect of lncRNA NORAD on vascular endothelial cell injury and atherosclerosis and potential mechanisms." (PMID 34307380, 2021). "Knockdown of lncRNA NORAD aggravated ox-LDL-reduced or atherosclerosis-decreased vascular endothelial growth factor (VEGF) expression in HUVECs and thoracic aorta of mice to ameliorate vascular endothelial cell injury and atherosclerosis development." (PMID 34307380, 2021). "Second, the potential mechanisms on how lncRNA NORAD regulates vascular endothelial cell injury and atherosclerosis should be further confirmed by an in vivo study." (PMID 34307380, 2021). "In a study about atherosclerosis (AS), lncRNA NORAD gene was determined to be at high expression in both oxidized low-density lipoprotein (ox-LDL) induced HUVECs and high fat diet (HFD)-treated mice, lncRNA NORAD gene knockdown was suggested to relieve vascular endothelial cell injury." (PMID 38167080, 2024). "NORAD modulates inflammation and atherosclerosis in various cardiovascular diseases." (PMID 36829193, 2023). "Also, lncRNA NORAD plays an essential role in vascular endothelial cell injury and atherosclerosis development." (PMID 35055117, 2022). "In addition, a few recent studies have revealed that lncRNA NORAD contributes to vascular endothelial cell injury and atherosclerosis." (PMID 34307380, 2021). "Therefore, all these data suggested that knockdown of lncRNA NORAD attenuated atherosclerosis in AS mice." (PMID 34307380, 2021). "It was hypothesized that lncRNA NORAD may regulate vascular endothelial cell injury and atherosclerosis through VEGF." (PMID 34307380, 2021). "Thus, the primary aim of this study was to investigate the effects of lncRNA NORAD on vascular endothelial cell injury and atherosclerosis and potential mechanisms." (PMID 34307380, 2021). "However, the mechanisms on how lncRNA NORAD regulates endothelial cell injury, atherosclerosis, and CAD remain unclear." (PMID 34307380, 2021).
atherosclerosis (continued). "By using this model, we found that NORAD knockdown significantly increased the serum levels of total TC, TG, and LDL-C levels, which are among the characteristics of lipid disorders in atherosclerosis." (PMID 32267831, 2020). "However, the effect of lncRNA NORAD on atherosclerosis remains unknown." (PMID 32267831, 2020). "The ApoE−/− mice were given Ad-NORAD or control Ad-EGFP injection after 8 weeks of HFD, and HFD was maintained for another 8 weeks to study the effect of NORAD knockdown on atherosclerosis development." (PMID 32267831, 2020). "Our laboratory determined immediately that NORAD knockdown induces cell cycle arrest and aggravates ox-LDL-induced cell senescence of HUVECs, which promotes Ox-LDL-induced vascular endothelial cell injury and atherosclerosis." (PMID 37517088, 2023). "First, lncRNA NORAD expression was increased in ox-LDL-treated HUVECs and thoracic aorta of AS mice, and knockdown of lncRNA NORAD alleviated vascular endothelial cell injury and atherosclerosis development in vitro and in vivo." (PMID 34307380, 2021). "The present study found that lncRNA NORAD expression was increased in ox-LDL-treated HUVECs and thoracic aorta of atherosclerotic mice, and knockdown of lncRNA NORAD alleviated vascular endothelial cell injury and atherosclerosis development in vitro and in vivo." (PMID 34307380, 2021). "However, no studies have reported the role of lncRNA NORAD in VEGF expression and function in endothelial cell injury, atherosclerosis, and CAD." (PMID 34307380, 2021).
pancreatic cancer (11 papers, 2017 to 2024). "Interestingly, NORAD has been proven to be overexpressed in a range of cancers, including pancreatic cancer and bladder cancer; in both cases, high expression of NORAD was associated with poor survival." (PMID 33722248, 2021). "Elevated expression of NORAD in pancreatic cancer tissues is linked to poor prognosis and may confer a malignant phenotype upon tumor cells." (PMID 29121972, 2017). "Recent studies have demonstrated that NORAD acts as an oncogene in multiple cancers including malignant melanoma, pancreatic cancer, NSCLC and glioblastoma." (PMID 34893064, 2021). "’s report, NORAD promotes the tumor cell migratory and invasive abilities in pancreatic cancer through modulation on the hsa-miR-125a-3p-metiated RhoA axis." (PMID 34551785, 2021). "For instance, lncRNA NORAD promotes pancreatic cancer metastasis through enhancing epithelial–mesenchymal transition via targeting hsa-miR-125a-3p to increase RhoA expression." (PMID 34307380, 2021). "NORAD increases epithelial–mesenchymal transformation and promotes pancreatic cancer metastasis via the NORAD/hsa-miR-125a-3p/RhoA axis." (PMID 32267831, 2020). "The effects of NORAD on pancreatic cancer cells were studied by overexpression and knockdown in vitro." (PMID 29121972, 2017). "The expression of NORAD was significantly higher in 75 pancreatic cancer samples than in 55 normal pancreas tissues (GSE15471 and GSE16515, p < 0.001)." (PMID 29121972, 2017). "To the best of our knowledge, we are the first to demonstrate that NORAD acts as a ceRNA of miR-125a-3p and that it is involved in regulating pancreatic cancer metastasis and invasion." (PMID 29121972, 2017). "For example, lncRNA NORAD was significantly upregulated in pancreatic cancer cells under hypoxia, indicating that it might be a potential factor in the genesis of pancreatic cancer." (PMID 36118856, 2022). "Moreover, lncRNA NORAD enhances pancreatic cancer metastasis through promoting epithelial–mesenchymal transition via targeting hsa-miR-125a-3p to increase RhoA expression." (PMID 34307380, 2021). "NORAD is highly expressed in pancreatic cancer tissues and upregulated in hypoxic conditions." (PMID 29121972, 2017). "NORAD upregulation is correlated with shorter overall survival in pancreatic cancer patients." (PMID 29121972, 2017). "Furthermore, NORAD overexpression promoted the migration and invasion of pancreatic carcinoma cells, while NORAD depletion inhibited EMT and metastasis in vitro and in vivo." (PMID 29121972, 2017). "Mechanistically, NORAD may function as a ceRNA to regulate the expression of RhoA through competition for miR-125a-3p, thus playing an oncogenic role in the pathogenesis of pancreatic cancer." (PMID 29121972, 2017). "We found that hypoxia can increase NORAD expression and stimulate EMT in pancreatic cancer cells and that NORAD promotes EMT and metastasis by regulating RhoA in a miR-125a-3p-dependent manner." (PMID 29121972, 2017).
hepatocellular carcinoma (8 papers, 2021 to 2023). A malignant tumor that arises from hepatocytes. "For instance, NORAD levels were found to be prominently increased in hepatocellular carcinoma (HCC) tissues and cells, serving as an oncogenetic factor in HCC." (PMID 35200103, 2022). "According to the relevant literature, NORAD is robustly expressed in hepatocellular carcinoma cells." (PMID 36245705, 2022). "Besides, NORAD up-regulation has enhanced migration and invasion of hepatocellular carcinoma cells through sponging miR-202-5p, which acts as a tumor-suppressor miRNA through the TGF-β pathway." (PMID 34485302, 2021). "However, in hepatocellular carcinoma, NORAD acts contradictorily as a tumor suppressor." (PMID 36514044, 2022).
osteosarcoma (8 papers, 2016 to 2025). A usually aggressive malignant bone-forming mesenchymal neoplasm, predominantly affecting adolescents and young adults. "NORAD knockdown suppressed the proliferation and invasion of osteosarcoma cells because NORAD acted as a sponge for miR-199a-3p." (PMID 37517088, 2023). "In osteosarcoma cell lines, NORAD regulates cancer cell features via acting as a molecular sponge for hsa-miR-199a-3p." (PMID 34485302, 2021). "NORAD plays an important role in regulating the function of osteosarcoma cells by competing with hsa-miR-199a-3p." (PMID 34257656, 2021). "By perturbing NORAD levels in osteosarcoma U2OS cells, we show that NORAD modulates the mRNA abundance of Pumilio targets, in particular those involved in mitotic progression." (PMID 27406171, 2016). "Moreover, lncRNA NORAD increases the sensitivity of osteosarcoma to cisplatin through targeting miR-410-3p." (PMID 34307380, 2021). "Moreover, growth of osteosarcoma tumors in animals has been attenuated by NORAD silencing in the implanted cells." (PMID 34485302, 2021).
prostate carcinoma (8 papers, 2020 to 2025). A carcinoma that arises from epithelial cells of the prostate gland. "Despite the supporting evidence offered in this prostate cancer study, the use of NORAD as a progression biomarker in NB requires a much deeper investigation at both the preclinical and clinical stages." (PMID 36983973, 2023). "MiR-30a-5p was downregulated in prostate cancer tissue, and long non-coding RNA activated by DNA damage (NORAD) was upregulated, while NORAD binds to and downregulates miR-30a-5p." (PMID 37569466, 2023). "Moreover, HyPR-MS maps prostate cancer complexes (MALAT1/NEAT1/NORAD), while TOBAP-MS identifies HULC’s 140 interactors in liver cancer, and BioID-MS links HOTAIR to ribosomes in breast cancer cell lines." (PMID 40861865, 2025). "Moreover, the lncRNA NORAD is highly expressed in prostate cancer cells and tissues and potentiates the secretion and uptake of prostate cancer EVs in recipient cells via regulating the miR-541-3p-pyruvate kinase M2 (PKM2) axis." (PMID 39585046, 2024). "In order to affect Wnt signaling in prostate cancer, NORAD targets miRNA-30a-5p." (PMID 35773731, 2022). "However, the impact of NORAD on progression of prostate cancer and its possible mechanisms are still largely unknown." (PMID 33292272, 2020). "HyPR-MS has been instrumental in locating prostate cancer-related complexes, including MALAT1, NEAT1, and NORAD." (PMID 40861865, 2025). "For example, NORAD sponges miR‐541‐3p and promotes PKM2 expression, which promotes prostate cancer bone metastasis through increased extracellular vesicle internalization." (PMID 35924724, 2023). "By binding to miRNA-30a-5p and acting as a ceRNA, NORAD upregulates expression level of RAB11A as a member of RAS oncogene family, resulting in Wnt/β-catenin activation and subsequent increase in metastasis of prostate cancer cells via EMT induction." (PMID 35773731, 2022).
cervical cancer (6 papers, 2020 to 2025). A primary or metastatic malignant neoplasm involving the cervix. "In our study, NORAD was highly expressed in OSCC tissues and cells, which was consistent with the finding that NORAD had high expression in cervical cancer." (PMID 34991683, 2022). "Over-expression of NORAD in cervical cancer patients has been correlated with higher stage, lymph nodes and vascular involvement, and poor survival." (PMID 34485302, 2021). "In cervical cancer cells, NORAD enhances expression of SIP1 to increase cell proliferation, invasiveness and EMT." (PMID 34485302, 2021). "Moreover, NORAD and ZFAS1 have been reported to promote cell invasion and migration in cervical cancer and bladder cancer, respectively, by up-regulating ZEB2." (PMID 36514044, 2022).
esophageal squamous cell carcinoma (6 papers, 2020 to 2024). Esophageal squamous cell carcinoma (ESCC) is a type of esophageal carcinoma (EC) that can affect any part of the esophagus, but is usually located in the upper or middle third. "In esophageal squamous cell carcinoma, NORAD expression is substantially upregulated compared to adjacent normal tissues, and high NORAD expression is associated with tumor size and advanced AJCC staging, according to studies." (PMID 37993524, 2023). "Besides, lncRNA NORAD was reported to upregulate esophageal squamous cell cancer radioresistance via miR-199-a1/EEPD1." (PMID 35600868, 2022).
malignant melanoma (6 papers, 2019 to 2021). "We also examined the effects and underlying mechanisms of NORAD expression in melanoma cells." (PMID 30843652, 2019). "Previous studies have demonstrated that NORAD promoted tumor proliferation and progression in non-small-cell lung cancer, endometrial cancer, and melanoma." (PMID 35047491, 2021). "An obviously upregulation of NORAD in the melanoma cell lines was observed comparing with the control human melanocytes, which implicated the upregulation of NORAD in MM." (PMID 30843652, 2019). "In the experiment involving nude mice, the downregulation of miR‐205 promoted growth of melanoma xenografts, while the knockdown of NORAD almost completely reversed the promotion of growth." (PMID 30843652, 2019). "In vitro, NORAD knockdown significantly inhibited migration and invasion of malignant melanoma cells and elevated the expression of miR‐205, there was an interaction between miR‐205 and NORAD in the RNA‐induced silencing complex." (PMID 30843652, 2019). "We observed high levels of NORAD in melanoma tissues and human malignant melanoma cells, particularly in metastatic MM." (PMID 30843652, 2019). "We validated the promoting effects of downregulated miR‐203 on human melanoma xenograft formation, while downregulation of NORAD mostly reversed these effects." (PMID 30843652, 2019). "In this study, high expression of NORAD was firstly observed in melanoma tissues and human malignant melanoma cell lines, our aim was to study the interaction of them in the process of invasion and migration of malignant melanoma cells." (PMID 30843652, 2019). "In addition, it has been found that overexpression of NORAD enhances the invasive and migratory capabilities of melanoma cells via competitive inhibition of miR-205." (PMID 34551785, 2021). "Downregulation of NORAD also restrained malignant melanoma cell migration and invasion." (PMID 33267910, 2020). "In malignant melanoma, NORAD may act as a sponge for miR‐205 and reduce the transcriptional repression of the miR-205 target gene EGLN2, a key regulator of ER stress." (PMID 33267910, 2020). "NORAD may play critical roles in tumorigenesis and progression of malignant melanoma by regulating of the miR‐205‐EGLN2 pathway, and may serve as a new therapeutic target." (PMID 30843652, 2019). "qRT‐PCR confirmed NORAD upregulation in melanoma tissues compared to normal tissues." (PMID 30843652, 2019). "However, whether NORAD-induced ER stress promotes the invasion and metastasis of melanoma cells needs to be further studied." (PMID 33267910, 2020).
neuroblastoma (6 papers, 2021 to 2024). Neuroblastoma (NB) is the most common solid, extracranial childhood tumor. "Research conducted with murine xenograft models showed that increased NORAD expression correlated negatively with the prognoses of patients with neuroblastoma." (PMID 38891878, 2024). "NORAD has increased proliferation, metastatic ability, and resistance to doxorubicin while inhibiting apoptosis and autophagy in neuroblastoma cells through targeting miR-144-3p." (PMID 34178658, 2021). "For instance, NORAD increases the growth of neuroblastoma tumors in animal models via miR-144-3p/HDAC8 axis." (PMID 34485302, 2021). "However, Yu and colleagues reported the contradictory finding that low NORAD expression was associated with poor survival, MYCN amplification, and high-risk neuroblastoma." (PMID 38891878, 2024). "Similarly, in DOX‐resistant neuroblastoma with upregulated NORAD and PTX‐resistant breast cancer with downregulated EGOT,56, 57 both autophagy and apoptosis levels were lower than in sensitive groups." (PMID 37837401, 2023). "Interestingly, NORAD overexpression relieves cytotoxicity and inflammatory responses of neuroblastoma cells after MPP + treatment." (PMID 35782387, 2022). "In MPP + -induced neuroblastoma cells, reduced NORAD expression is observed." (PMID 35782387, 2022). "have demonstrated up-regulation of NORAD in neuroblastoma tissues and cell lines." (PMID 34178658, 2021). "NORAD upregulates the expression of histone deacetylase 8 (HDAC8) by sequestering its natural inhibitory miRNA miR-144-3p, thereby promoting neuroblastoma cell proliferation, metastasis, and doxorubicin resistance while inhibiting apoptosis and autophagy." (PMID 38891878, 2024). "As well as that, NORAD, SNHG7, and SNHG16 have been shown to be involved in conferring this phenotype in neuroblastoma." (PMID 34178658, 2021).
glioma (5 papers, 2019 to 2025). A benign or malignant brain and spinal cord tumor that arises from glial cells (astrocytes, oligodendrocytes, ependymal cells). "For example, in glioma cells, it has been shown that the association of NORAD and AKR1B1 activates the ERK pathway, promoting a malignant phenotype." (PMID 33739352, 2021). "In human glioma cells, high expression of AKR1B1 was found to be associated with the upregulation of NORAD (non-coding RNA activated by DNA damage)." (PMID 39055885, 2024). "High expression of AKR1B1 and NORAD was seen in glioma cells." (PMID 39055885, 2024).
non-small cell lung carcinoma (5 papers, 2020 to 2022). A group of at least three distinct histological types of lung cancer, including non-small cell squamous cell carcinoma, adenocarcinoma, and large cell carcinoma. "Noticeably, the expression of NORAD is elevated in cisplatin-resistant non-small-cell lung cancer cells, contributing to chemoresistance." (PMID 34969360, 2022). "Furthermore, upregulation of NORAD contributes to cisplatin resistance in non-small-cell lung cancer." (PMID 34969360, 2022).
bladder cancer (4 papers, 2020 to 2022). "The high expression of NORAD has been previously linked with enhanced metastatic potential and clinical progression of bladder cancer, resulting in poor prognosis." (PMID 33722248, 2021).